ENSG00000281181 (novel transcript, similar to YY1 associated myogenesis RNA 1 YAM1)
Gene: Long non-coding RNA gene on chromosome 21 (8,437,629 to 8,438,551, reverse strand). Ensembl gene ENSG00000281181.
Gene Ontology:
Molecular function: structural constituent of ribosome
Cellular component: ribosome